APC (APC regulator of Wnt signaling pathway)
Diseases named in the same sentence as APC in open-access papers (continued):
Sharing a sentence is not in itself a finding about the gene and the disease.
colorectal cancer (continued). "In colorectal cancer, loss-of-function mutations of the APC gene led to stabilization and accumulation of β-catenin and constitutive transcriptional activation of Wnt/β-catenin target genes through TCF/LEF:β-catenin activity." (PMID 35663403, 2022). "TRAF-binding protein domain (TRABID) was demonstrated to bind and cleave Lys63-linked ubiquitin moieties on APC tumor suppressor substrates, which led to the disruption of APC and activation of Wnt signaling in colorectal cancer cell lines." (PMID 35874839, 2022). "The Wnt signaling pathway is a key pathway in colorectal cancer pathogenesis and is constitutively active in APC mutated colon cancer cells." (PMID 36067202, 2022). "In fact, more than 80% of colorectal cancer had an inactivated APC gene, rendering it the most prevalent mutation in colorectal cancer." (PMID 36421339, 2022). "Another study demonstrated that knocking down PKR or using PKR inhibitors suppressed the growth of APC-mutated colorectal cancer which favored the oncogenic role of PKR." (PMID 36038948, 2022). "For instance, mutations of APC occur as an early driving event in colorectal carcinogenesis and can be observed in ~50% of sporadic colorectal cancers." (PMID 35327645, 2022). "APC is a tumor-suppressor gene and its deletion and point mutations correlate to the development of numerous types of cancers, especially colorectal cancers." (PMID 36011019, 2022). "An important disease-related phenotypethat requires organelle-levelanalytical precision is the mutations of adenomatous polyposiscoli (APC), which drive 80% of the sporadiccases of colorectal cancer." (PMID 36589880, 2022). "In 1999, it was already demonstrated that PPARβ/δ was overexpressed in colorectal cancers (CRC) with adenomatous polyposis coli (APC)/β-catenin mutations, leading to the prevention of apoptosis in colon cancer cells." (PMID 35954274, 2022). "Loss or inactivation of adenomatous polyposis coli (APC) results in constitutive stimulation of Wnt/β-catenin signaling, which is considered a precursor to colorectal cancer." (PMID 36363555, 2022). "Deletion of APC or activating mutation of beta‐catenin is an early event in colorectal carcinomas (> 75%), pointing out that these cancers largely depend on Wnt signaling activation." (PMID 34890102, 2022). "One of the most important mutations within the Wnt/β-catenin pathway are mutations of the adenomatous polyposis coli (APC) gene in colorectal carcinoma, which influence downstream β-catenin; however, APC mutations play a subordinate role in HCC." (PMID 36010583, 2022). "In the colorectal cancer-driving APC gene, 5.3% of the mutations display the extended motif characteristic for colibactin-induced mutations (SBS88/ID18), implying a causative role for pks+E." (PMID 34745228, 2021). "This process has been described in colorectal cancer cells with mutations of the APC (adenomatous polyposis coli) gene, which encodes a protein crucial for the maintenance of mitotic microtubule spindles." (PMID 34680300, 2021). "Mutations in APC gene are the basis of hereditary predisposition to colorectal cancer in familial adenomatous polyposis coli (FAP) and also the primary reason for the formation of sporadic colorectal tumors." (PMID 33237662, 2021).
colorectal cancer (continued). "It is known that the development of colorectal cancer is associated with mutation in the adenomatous polyposis coli (APC) gene." (PMID 34677457, 2021). "Germ line APC mutations underlie the highly penetrant colorectal cancers (CRCs) associated with familial adenomatous polyposis (FAP) whereas acquired APC mutations are extremely common in sporadic human CRC." (PMID 33808495, 2021). "It was demonstrated that human colorectal cancer is a multi-step genetic process and that the mutation of the APC gene occurs at the beginning of the carcinogenesis process." (PMID 33916402, 2021). "Consistently, knockdown of TFEB in HT29 cells (a colorectal cancer cell line that has an APC mutation) resulted in reduced expression of ‘TFEB mediated Wnt target genes’." (PMID 33753903, 2021). "Although cancer is a more complex genetic disease with hundreds of gene mutations, it was recently demonstrated that repair the APC mutation restores intestinal crypt homeostasis in a mouse colorectal cancer model and in organoids derived from this model." (PMID 34033245, 2021). "Even in cases of sporadic colorectal cancer, loss of functional APC is typically the first mutational event to occur." (PMID 33620068, 2021). "The WNT/β-catenin signalling pathway has recently gained attention for its effects on TNBC, despite absence of recurrent β-catenin mutations or classical genetic lesions associated with this pathway’s overactivation, such as APC loss in colorectal cancer." (PMID 34863149, 2021). "Familial adenomatous polyposis (FAP) is an inherited syndrome caused by a heterozygous adenomatous polyposis coli (APC) germline mutation, associated with a profound lifetime risk for colorectal cancer." (PMID 33664379, 2021). "FAP is an autosomal-dominant colorectal cancer syndrome, caused by a germline mutation in the APC gene, characterized by hundreds of adenomatous colorectal polyps, with an almost inevitable progression to colorectal cancer at an average age of 35–40." (PMID 34552058, 2021). "For example, for individuals of Ashkenazi Jewish ancestry, the APC p.I1307K increased risk allele indicates an elevated risk of colorectal cancer that warrants modifications to clinical management." (PMID 34404389, 2021). "Mutations in the critical regulatory switches of the Wnt signaling pathway have been implicated in multiple cancers and loss of APC is a hallmark of colorectal cancer initiation and progression." (PMID 34552611, 2021). "CIN is a feature of the evolution of aggressive colorectal adenocarcinoma right from the outset, being evident in the smallest adenomas, and multiple reports have directly linked oncogenic APC mutations in colorectal cancer with a predisposition to CIN." (PMID 33335067, 2021). "SW480 colorectal cancer cells, which have high Wnt signaling caused by the loss of APC, also displayed increased macropinocytosis." (PMID 33619734, 2021). "The majority of colorectal cancer (CRC) patients carry mutations in the APC gene, which lead to the unregulated activation of the Wnt pathway." (PMID 34609520, 2021). "For example, loss of APC expression, frequently identified in colorectal cancer, is associated with poor prognosis." (PMID 34356615, 2021). "Driver analysis identified the Wnt pathway gene APC as the only consistently mutated driver in colorectal cancer." (PMID 33632293, 2021). "APC is usually associated with the development of colorectal cancer or, when germline mutant, with the familial adenomatous polyposis (FAP)." (PMID 34262869, 2021).
colorectal cancer (continued). "Because similar APC mutations are found in the majority of spontaneous human colorectal cancers, APCMin/+ mice are used as a general model for the early stages of colorectal cancer." (PMID 33557356, 2021). "APC mutations have been frequently detected in colorectal cancers but with a considerably lower frequency in some other types of cancers." (PMID 34155197, 2021). "APC is a key tumor suppressor of colorectal cancer, where its mutation often correlates with loss of heterozygosity and with nuclear localization of beta-catenin." (PMID 34680217, 2021). "APCMin/+ mice are a genetic model of colorectal cancer that develop spontaneous multiple intestinal adenomas, resembling humans carrying germ-line mutations in APC." (PMID 33901189, 2021). "Of the two, many mutations in Wnt signaling, including loss of function of APC and gain of function β-catenin which result in sustained Wnt-signaling activation, are found in colorectal cancers." (PMID 33430034, 2021). "Lack of β-catenin regulation leads to the transformation of specific subtypes of colorectal cancers, for example tumors carrying mutations in the adenomatous polyposis coli (APC), a member of the β-catenin destruction complex." (PMID 33430387, 2021). "The mutation of APC leads to overactivation of Wnt signaling pathways resulting in 80% of colorectal cancer prognosis." (PMID 33597969, 2021). "Most human colorectal cancers have somatic mutations in the adenomatous polyposis coli (APC) tumor suppressor gene, and APCMin/+ mice develop multiple intestinal neoplasia." (PMID 33037985, 2021). "Given its prevalence, uncovering the wider effects of an inactivating APC mutation is important to fully understand colorectal cancers and aid the development of more effective personalised treatments." (PMID 33620068, 2021). "In sporadic colorectal cancer, the hypermethylation of CpG island in APC is even considered as one of the primary causative factors." (PMID 33968756, 2021). "The well-known APC gene for colorectal cancer 30 showed a higher mutation frequency (N0: 65.6%, N1: 79.8%; p = 0.042) in patients with regional lymph node metastasis." (PMID 35003350, 2021). "Our study demonstrated the known driver mutations seen in colorectal cancer such as APC, KRAS, BRAF and PIK3CA, but also more novel mutations that would potentially be targetable by molecular agents." (PMID 33632293, 2021). "It was found that this aberrant activation of Wnt signaling in colorectal cancer was due to the loss of function mutations in the APC gene or point mutation in the N-terminal sites of β-catenin that leads to the stabilization of β-catenin." (PMID 33968932, 2021). "More than 80% of colorectal cancer patients have adenomatous polyposis coli (APC) mutations, which induce abnormal WNT/β-catenin activation." (PMID 34298950, 2021). "The patients with FAP have one mutated copy of the APC gene and carry a near 100% lifetime risk of developing colorectal cancer." (PMID 33620068, 2021). "In order to better understand the contribution of RAC1-GEFs to phenotypes associated with APC deficiency in colorectal cancer in vivo, we have undertaken comparative transcriptional profiling of APC deficient and control intestinal tissues." (PMID 33397922, 2021).
colorectal cancer (continued). "APC is a well-known gene that are often mutated in colorectal cancer, and the mutation frequency was significantly higher in left-sided tumors for both of Korean (left: 77.6%, right: 57.4%, p = 0.013) and Caucasian (left: 84.3%, right: 60.8%, p=0.001)." (PMID 35003350, 2021). "In most colorectal cancers, both the alleles of APC gene are mutated, especially in the region required for interaction with the armadillo (arm) repeats of β-catenin." (PMID 34552611, 2021). "The rate of protein synthesis is increased by cancer-associated mutations in colorectal cancer, such as APC (APC regulator of WNT signaling pathway) loss or KRAS (KRAS proto-oncogene) mutation." (PMID 33855169, 2021). "Inactivating mutations in the APC gene have been reported in 34–70% of sporadic colorectal cancer patients." (PMID 34439344, 2021). "Ninety percent of colorectal cancers produce β-catenin and APC mutations responsible for Wnt pathway activation." (PMID 34452555, 2021). "One of the oncogenes for colorectal cancer is Adenomatous Polyposis Coli (APC), whose mutations have been detected in more than 30% of colon cancer patients." (PMID 34017824, 2021). "In the study of Güler, 8 of 20 patients with colorectal carcinoma reported that there was a mutation in the APC gene, whereas in the rest, the expression of the APC gene was significantly different compared to the control group." (PMID 33237662, 2021). "Increased expression of Axin2 was found after the loss of adenomatous polyposis coli (APC), a key tumour suppressor gene, in colorectal cancer, and the knockdown of Axin2 attenuated oncogenic and Wnt signalling activities in cancer cells." (PMID 33046030, 2020). "In these studies, it was found that the APC protein is mutated and inactivated in colorectal cancers, typically in the early stages of cancer development." (PMID 33143142, 2020). "Among the recurrent mutations in colorectal cancers, APC and KRAS mutations were common between adenomas and carcinomas, indicative of their early occurrence during genomic evolution." (PMID 32023847, 2020). "Mutation of the APC gene is a common early event in CRC but is reported at lower rates in early-onset colorectal cancer (EOCRC) than in older patients." (PMID 33352971, 2020). "It has been found that the occurrence of colorectal cancer is related to the uncontrolled accumulation of intracellular β-catenin and the mutation of APC." (PMID 33310972, 2020). "Our goal was to determine how mutations in APC drive colorectal cancer (CRC) development in humans by causing colonic stem cell (SC) overpopulation." (PMID 33112876, 2020). "The first one is dominant in e.g., colorectal cancers and hepatocellular carcinoma, with loss-of-function mutations in APC prevalent in the former, and gain-of-function mutations in β-catenin or loss-of-function mutations in Axin prevailing in the latter." (PMID 32131438, 2020). "Inactivation of the destruction complex is well studied and exemplified by the prominent driver role of APC mutations in colorectal cancer." (PMID 32965059, 2020). "Compared to colorectal cancer, somatic mutations in the APC gene are observed at a much lower frequency, ranging between 0 and 33%." (PMID 32357859, 2020). "It is worth mentioning that APC (adenomatous polyposis coli) gene mutations (the most common alterations present in colorectal cancer) most presumably lead to an accumulation of ß-catenin, and then to an aberration of the WNT signaling pathway." (PMID 32260235, 2020).
colorectal cancer (continued). "During colorectal cancer development, mutation of the APC or β-catenin genes in the Wnt signaling pathway is the first crucial molecular event, and such mutation causes oncogenic stress." (PMID 32962187, 2020). "RNF43 mutations, found in ~19% of colorectal cancer cases, are mutually exclusive to APC mutations and considered a prime hallmark of Wnt‐hypersensitive cancer subsets." (PMID 32965059, 2020). "In colorectal cancer, an early mutation leading to such features usually occurs in the APC or CTNNB1 genes, thereby activating Wnt signalling." (PMID 33292279, 2020). "This discovery was swiftly followed by the creation of APC mutant mouse models which represent not only FAP but also spontaneous colorectal cancers, 80% of which feature mutations in APC." (PMID 32325966, 2020). "Collectively, these data indicate that the activating mutation of BRAF and the truncating mutation of APC represent an aggressive subtype of colorectal cancers that occur at a relatively young age in comparison to BRAF mutant cancers more generally." (PMID 32384699, 2020). "High frequency of mutations causing hyperactivation of WNT-signaling can be detected for example in colorectal cancer and mutations in APC leading to APC loss of function have been found in about 70% of cases." (PMID 32659938, 2020). "The Apc min/+mice (the mice model with adenomatous polyposis coli (APC) gene mutation) gavaged with feces from colorectal cancer patients had more intestinal tumors compared with healthy controls or the mice gavaged with phosphate-buffered saline." (PMID 33330121, 2020). "There was evidence showing that APC mutation was a positive prognostic factor in colorectal cancer, especially in proximal tumors, which was consistent with our results." (PMID 33194656, 2020). "Mutations in TMPRSS13 have been previously identified in colorectal adenomas, and their regional presentation in our study (lesion-common mutations) indicates that TMPRSS13 mutations in colorectal cancers can be early events like APC or KRAS mutations." (PMID 32023847, 2020). "The frequency of APC mutations, which occur at a high frequency in colorectal cancer, in our cohort was lower than previously observed (12.4%)." (PMID 32087721, 2020). "Wnt signaling activation in colorectal cancer is induced mainly by APC (73%) and CTNNB1 (5%) mutations, suggesting that canonical Wnt/β-Catenin signaling is the leading form of Wnt signaling in colorectal cancer." (PMID 33234169, 2020). "Truncating mutations in the tumour suppressor gene APC occur frequently in colorectal cancers and result in the deregulation of Wnt signalling as well as changes in cell-cell adhesion." (PMID 33057364, 2020). "The Wnt/β-catenin signaling pathway is deregulated in nearly all colorectal cancers (CRCs), predominantly through mutation of the tumor suppressor Adenomatous Polyposis Coli (APC)." (PMID 32751567, 2020). "Another source of anticancer drugs is natural products, which normally seem to be more effective and/or less toxic.Approximately 80% of colorectal cancers are related with mutations in a gene called APC that result in high levels of the β-catenin protein." (PMID 32405167, 2020). "It is widely accepted that almost 80% of the colorectal cancer (CRC) patients harbor inactivating mutations in the APC gene along with β-catenin mutations that result in hyperactivation of the Wnt signaling pathway." (PMID 33126517, 2020).